PARP10 (poly(ADP-ribose) polymerase family member 10)
Description:
ADP-ribosyltransferase that mediates mono-ADP-ribosylation of glutamate and aspartate residues on target proteins. In contrast to PARP1 and PARP2, it is not able to mediate poly-ADP-ribosylation. Catalyzes mono-ADP-ribosylation of GSK3B, leading to negatively regulate GSK3B kinase activity. Involved in translesion DNA synthesis in response to DNA damage via its interaction with PCNA.
Synonyms: ARTD10; FLJ14464
Tractability: Small molecule: a structure with a bound ligand is known; a high-quality ligand is known; it has a high-quality binding pocket. PROTAC: ubiquitination databases record sites on it; its protein half-life has been measured; a small molecule that binds it is known.
Target class: Enzyme; Transferase
Gene: Protein-coding gene on chromosome 8 (143,977,153 to 144,019,930, reverse strand). Ensembl gene ENSG00000178685.
Subcellular location: Nucleus, nucleolus; Cytoplasm
Subcellular location (Human Protein Atlas): Nucleoli rim; Cytosol; Golgi apparatus
Pathways (Reactome):
Disease: Maturation of nucleoprotein
Metabolism: Nicotinate metabolism
Gene Ontology:
Molecular function: DNA-binding transcription factor binding; K63-linked polyubiquitin modification-dependent protein binding; NAD+ poly-ADP-ribosyltransferase activity; NAD+-protein mono-ADP-ribosyltransferase activity; NAD+-protein-aspartate ADP-ribosyltransferase activity; NAD+-protein-glutamate ADP-ribosyltransferase activity; NAD+-protein-lysine ADP-ribosyltransferase activity; protein binding; transcription corepressor activity
Biological process: chromatin organization; negative regulation of canonical NF-kappaB signal transduction; negative regulation of fibroblast proliferation; negative regulation of gene expression; negative regulation of protein K63-linked ubiquitination; protein auto-ADP-ribosylation; protein poly-ADP-ribosylation; translesion synthesis; nicotinate metabolic process; viral protein processing; negative regulation of DNA-templated transcription
Cellular component: cytoplasm; cytosol; nucleolus; nucleus
Genetic constraint (gnomAD): Loss-of-function variants: 56 observed, 76.89 expected, observed/expected ratio (o/e) 0.73, 90% interval 0.59 to 0.91. The upper end of that interval is the gene's LOEUF score, 0.91, which puts it in group 3 of 6, group 1 being the genes least tolerant of losing a copy. Missense variants: 1,227 observed, 1,314.7 expected, observed/expected ratio (o/e) 0.93, 90% interval 0.89 to 0.98. Synonymous variants: 576 observed, 573.08 expected, observed/expected ratio (o/e) 1.01, 90% interval 0.94 to 1.08.
Homologues: Orthologues: chimpanzee PARP10 (98% identical), macaque PARP10 (93% identical), guinea pig PARP10 (65% identical), rat Parp10 (63% identical), mouse Parp10 (63% identical), zebrafish parp10 (28% identical), tropical clawed frog parp10 (27% identical). Paralogues in human: PARP14 (19% identical), PARP15 (11% identical), PARP12 (9% identical), PARP9 (9% identical), TIPARP (8% identical), ZC3HAV1 (7% identical), PARP11 (7% identical), ZC3HAV1L (2% identical).
Diseases named in the same sentence as PARP10 in open-access papers:
PARP10 is named in the same sentence as 34 diseases in open-access papers, as found by Europe PMC text mining. Sharing a sentence is not in itself a finding about the gene and the disease. The quoted sentences say what the papers report.
cardiac hypertrophy (15 papers, 2021 to 2025). "This causes a blockage of the YTHDF2-mediated degradation of the PARP10 mRNA transcripts and an increase in PARP10 expression, which leads to cardiac hypertrophy." (PMID 38112620, 2023). "Cardiac hypertrophy-associated piRNAs have been shown to induce cardiomyocyte hypertrophy and poor cardiac remodeling by blocking m6A RNA methylation of PARP10." (PMID 35093098, 2022). "Additionally, by interacting with METTL3 and inhibiting its RNA methylation activity, cardiac-hypertrophy-associated piRNA (CHAPIR) prevents the m6A modification of PARP10 mRNA." (PMID 38112620, 2023). "This inhibition leads to the up-regulation of poly (ADP-ribose) polymerase family member 10 (Parp10) expression by suppressing the m6A modification of Parp10 mRNA, consequently inducing myocardial hypertrophy." (PMID 40247912, 2025). "This methylation enhances PARP10 expression in cardiomyocytes, facilitating pathological cardiac hypertrophy in response to pressure overload." (PMID 38706718, 2024). "A recent study demonstrated that cardiac-hypertrophy-associated piRNA (CHAPIR), a PIWI-interacting noncoding RNA (piRNA), directly interacts with Mettl3 to inhibit the m6A RNA methylation of Parp10 mRNA." (PMID 38706718, 2024). "CHAPIR regulates the cardiac hypertrophy by controlling the METTL3 dependent m6A methylation of PARP10 mRNA." (PMID 34489709, 2021). "PiRNA CHAPIR promotes cardiac hypertrophy through METTL3-mediated m6A modification of Parp10 mRNA." (PMID 35191812, 2022). "However, METTL3 knockdown also accelerates heart failure progression by promoting pathological cardiac hypertrophy through upregulating the expression of PARP10." (PMID 35836571, 2022). "Cardiac hypertrophy-associated PIWI-interacting RNA (CHAPIR) competitively binds METTL3 and blocks m6A methylation of polymerase family member 10 (PARP10), while up-regulation of PARP10 facilitates glycogen synthesis and pathological cardiac hypertrophy by inhibiting the kinase activity of GSK-3β." (PMID 36830642, 2023). "In contrast, METTL3 knockout accelerates pathological cardiac hypertrophy and heart failure by reducing m6A levels of poly (ADP-ribose) polymerase family member 10 (Parp10) mRNA and increasing PARP10 expression." (PMID 41446042, 2025). "CHAPIR directly interacted with METTL3 which suppresses the m6A modification of Parp10 mRNAs thereby increasing Parp10 protein levels and promoting NFATC4‐induced pathological cardiac hypertrophy." (PMID 35718942, 2022).
hepatocellular carcinoma (9 papers, 2021 to 2025). A malignant tumor that arises from hepatocytes. "A deficiency of PARP10 promotes the migration and invasion of HeLa cells and hepatocellular carcinoma (HCC) QGY-7703 cells in vitro and enhances the in vivo metastasis of these cells in a mouse model." (PMID 36313419, 2022). "Previous studies demonstrated that PARP10 functions as an oncogene in Hela cells, while acting as a tumor suppressor in hepatocellular carcinoma cells, indicating that it has a dual role in carcinogenesis, in a context-dependent manner." (PMID 37506247, 2023). "To this end, we quantified the percentage of the mitotic population in HeLa (ovarian cancer), A375 (melanoma), U2OS (osteosarcoma), T47D (breast cancer) and HepG2 (hepatocellular carcinoma) cells treated with the PARP10 specific inhibitor OUL35." (PMID 36358629, 2022). "In hepatocellular carcinoma (HCC), elevated levels of PLK1 inhibit PARP10 activity, which in turn, allows activation of the NF-κB pathway through NEMO." (PMID 40741921, 2025). "Furthermore, in hepatocellular carcinoma, the inhibition of NEMO ubiquitination by PARP10 is negatively regulated by PLK1-mediated phosphorylation of PARP10." (PMID 34725336, 2021).
viral infection (7 papers, 2019 to 2025). "The results revealed that, upon viral infection, the mRNA levels of NAD+-consuming enzymes, including Sirt1-7, Parp1, Parp10, Parp12, Parp14, and CD38, were substantially upregulated." (PMID 40006932, 2025). "PARP1–3 are activated by DNA damage, whereas the mono-ARTs PARP10, PARP11 and PARP12 are upregulated during viral infection leading to translational shut-down." (PMID 36018800, 2022). "Herein, the candidate genes PARP10, EXOSC4, GFUS and EEF1D, involved in various viral infections, were identified." (PMID 33255903, 2020). "In order to figure out whether mRNAs and miRNAs in the ceRNA network have effects on viral infection, we investigated the effect of selected six representative mRNAs (CMPK2, ISG15, PARP10, SAMD9, GBP1, and RIG-I) involved in the ceRNA network upon HTNV infection." (PMID 32232013, 2020). "For instance, transcriptional induction of noncanonical PARP isoforms (e.g., PARP10, PARP12), along with NAD+ depletion, has been observed across viral infections, including coronaviruses, where similar activation of MARylating PARPs contributes to NAD+ loss." (PMID 41362627, 2025).
ovarian carcinoma (6 papers, 2021 to 2026). A malignant neoplasm originating from the surface ovarian epithelium. "PARP10 amplification and/or increased expression correlated with sensitivity to carboplatin and rucaparib, which was confirmed in the TCGA ovarian cancer dataset where it associated with platinum response." (PMID 33804647, 2021). "We also identified that common gene amplifications in ovarian cancers, like PARP10, associated with platinum response." (PMID 33804647, 2021). "Interestingly, cell line and TCGA ovarian cancer data analysis identified genomic amplification and/or high PARP10 expression to be associated with platinum-based drug response, which needs further exploration." (PMID 33804647, 2021). "Re-expressing PARP10 in ALYREF-depleted ovarian cancer cells rescued cell growth, proliferation, invasion, and migration to some extent." (PMID 41326692, 2026). "Our RT-qPCR results also showed that PARP10 was significantly downregulated upon ALYREF depletion in ovarian cancer cells." (PMID 41326692, 2026). "In this study, we report the function of ALYREF-mediated regulation of PARP10 mRNA stability by LLPS in ovarian cancer." (PMID 41326692, 2026). "In this study, we found that PARP10 was significantly overexpressed in ovarian cancer tissues and significantly related to the poor prognosis of patients." (PMID 41326692, 2026). "Consistently, higher PARP10 expression also predicted worse prognosis for ovarian cancer patients (Fig. EV8D)." (PMID 41326692, 2026). "The meRIP assay showed that m5C modification of PARP10 mRNA was reduced when NSUN2 was knocked down in ovarian cancer cells." (PMID 41326692, 2026). "Together, these findings suggest that ALYREF phase separation facilitates the malignant progression of ovarian cancer by promoting PARP10 expression and thereby enhancing PARP10-dependent proliferative pathways in a m5C-dependent manner." (PMID 41326692, 2026). "Using a multi-omics strategy, we identified PARP10 as a critical target of ALYREF in ovarian cancer." (PMID 41326692, 2026). "Western blotting verified that PARP10 protein was significantly decreased in ovarian cancer cells following ALYREF depletion." (PMID 41326692, 2026). "PARP10 is overexpressed in a significant proportion of tumors, particularly breast and ovarian cancers." (PMID 36187556, 2022). "PARP10 was amplified/highly expressed among 44% of ovarian cancers, of which 42% were platinum sensitive, and only 9% were resistant." (PMID 33804647, 2021). "Two DDR gene expression clusters correlating with treatment response were identified, with PARP10 identified as a novel marker of platinum response, which was confirmed in The Cancer Genome Atlas (TCGA) ovarian cancer cohort." (PMID 33804647, 2021). "Thus, we next assessed the effect of ALYREF on the stability of PARP10 mRNA in cells treated with actinomycin D. The results indicated that knocking down ALYREF decreased the stability of PARP10 mRNA in ovarian cancer cells." (PMID 41326692, 2026). "ALYRFE and PARP10 were highly expressed in ovarian cancer tissues." (PMID 41326692, 2026). "Knocking down PARP10 restrained the growth, migration, and invasion of ovarian cancer cells." (PMID 41326692, 2026). "ALYREF expression was positively correlated with PARP10 expression in ovarian cancer." (PMID 41326692, 2026). "In addition, RNA fluorescence in situ hybridization assays showed that PARP10 mRNA was localized in ALYREF condensates in the nucleus of ovarian cancer cells (Fig. EV5H)." (PMID 41326692, 2026). "To examine whether LLPS was involved in ALYREF regulation of PARP10 expression, we constructed GFP-ALYREF and its respective truncated forms in which IDRs were depleted or mutated and transfected the constructs into ovarian cancer cells." (PMID 41326692, 2026). "In addition, NSUN2 knockdown decreased PARP10 expression in ovarian cancer cells (Fig. EV4J,K)." (PMID 41326692, 2026). "Finally, ALYREF and PARP10 expression correlate with poor prognosis in ovarian cancer patients." (PMID 41326692, 2026).
ovarian carcinoma (continued). "PARP10 or ALYREF knockdown decreased the phosphorylation level of PI3K and AKT in ovarian cancer cells." (PMID 41326692, 2026). "Regarding PARP10, its established role in cellular proliferation and carcinogenesis may suggest that PARP10 inhibitors could also be employed in cancer treatment, particularly breast and ovarian cancers, since PARP10 is specifically overexpressed in those tumors." (PMID 36814782, 2023). "PARP10 amplification co-occurred with RECQL4 amplification, both located on Chr 8q24.3, in both cell lines and ovarian cancers (TCGA)." (PMID 33804647, 2021). "The correlation between PARP10 and ALYREF RNA expression was analyzed in ovarian cancer tissues." (PMID 41326692, 2026). "RIP assays showed that MTR4 did not bind PARP10 mRNA in ALYREF-expressing ovarian cancer cells (Fig. EV4C)." (PMID 41326692, 2026). "To test this, we detected the activity of PI3K and AKT upon ALYREF depletion or PARP10 depletion, and the results revealed that either ALYREF depletion or PARP10 depletion significantly decreased the phosphorylation levels of PI3K and AKT in ovarian cancer cells (Fig. EV4A,B)." (PMID 41326692, 2026). "Moreover, overexpressing ALY-wt but not ALY-mut promoted PARP10 expression at both the RNA and protein levels in ovarian cancer cells." (PMID 41326692, 2026). "Notably, MTR4 knockdown restored PARP10 mRNA but not protein expression in ALYREF-depleted ovarian cancer cells." (PMID 41326692, 2026). "These genes may potentially represent novel targets for personalized breast and ovarian cancer therapy, since their targeting should only inhibit proliferation of PARP10-overexpressing tumor cells, but should not affect the survival of normal tissues." (PMID 36187556, 2022). "Since PARP10 is overexpressed in a significant proportion of breast and ovarian cancer tumors, we reasoned that our screening setup may mimic the situation in cancer patients, with PARP10 being overexpressed in the tumor cells but not in the normal tissue." (PMID 36187556, 2022). "We also hypothesized that the potential clinical applicability of this screen goes beyond breast and ovarian cancer, since it may identify genes which can be targeted for cancer therapy in combination with PARP10 inhibitors, regardless of the PARP10 overexpression status." (PMID 36187556, 2022).
breast tumors (4 papers, 2017 to 2026). "By analyzing publicly-available TCGA datasets, we previously showed that PARP10 is overexpressed in about a third of all ovarian tumors and a fifth of all breast tumors." (PMID 36187556, 2022). "Moreover, previous analysis of the TCGA database revealed that PARP10 expression is increased in 19% of breast tumors, and its overexpression facilitates cell proliferation and tumor progression." (PMID 41326692, 2026). "Moreover, PARP10 depletion in BRCA1-mutant breast tumor-derived MDA-MB-436 cells also increased gap formation upon exposure to 0.4 mM HU or 150 μM cisplatin." (PMID 39043663, 2024). "Finally, by mining publicly available cancer datasets, we showed that PARP10 is overexpressed in about a third of all ovarian tumors and a fifth of all breast tumors." (PMID 36187556, 2022).
oral squamous cell carcinoma (4 papers, 2022 to 2026). "Recent studies detailing the possibilities of PARP10 inhibitors as anti-cancer agents have proven promising, showing that siRNA-targeted PARP10 repressed growth and metastatic capabilities in oral squamous cell carcinoma by negating its ability to regulate cell proliferation and apoptosis." (PMID 37508568, 2023). "Depletion of PARP10 impaired the PI3K-AKT and MAPK signaling pathways in oral squamous cell carcinoma." (PMID 41326692, 2026).
breast carcinoma (3 papers, 2018 to 2022). "Similar results were obtained in a different cell model: the breast cancer cell line T47D was transiently devoid of PARP10 expression, further confirming the involvement of this MARylating enzyme during mitotic progression." (PMID 36358629, 2022). "We speculate that this mimics the situation in breast cancer patients, with the normal breast tissue having normal PARP10 expression, and the breast cancer cells overexpressing PARP10." (PMID 36187556, 2022).
ovarian tumors (3 papers, 2022 to 2023). "Moreover, elevated levels of PARP10 have been observed in up to 19% of breast tumors and 32% of ovarian tumors, as revealed in The Cancer Genome Atlas (TCGA) database." (PMID 36313419, 2022). "Increased PARP10 expression has been reported in breast and ovarian tumors." (PMID 36313419, 2022). "Since PARP10 is mostly overexpressed in breast or ovarian tumors, we first created an isogenic PARP10 overexpression genetic system by exogenously expressing PARP10 under the doxycycline-inducible TRE promoter in the non-cancer breast epithelial cell line MCF10A." (PMID 36187556, 2022). "The functions of PARP10 appear to be distinct than those of PARP1, and its catalytic activity is not affected by PARP1 inhibitors, which have been recently approved for treatment of breast and ovarian tumors with BRCA mutations." (PMID 36187556, 2022).
gastric cancer (2 papers, 2018 to 2022). A primary or metastatic malignant neoplasm involving the stomach. "By analyzing an online database we showed that lower PARP10 expression increases survival in gastric cancer." (PMID 29293500, 2018). "In support, in gastric cancer, high PARP10 expression is correlated with shorter survival." (PMID 36313419, 2022).
leukemia (2 papers, 2018 to 2023). A malignant (clonal) hematologic disorder, involving hematopoietic stem cells and characterized by the presence of primitive or atypical myeloid or lymphoid cells in the bone marrow and the blood. "Future in vitro and in vivo studies are warranted to dissect the role of PARP10 on leukemia initiation and disease progression." (PMID 37506247, 2023).
melanoma (2 papers, 2020 to 2022). A malignant, usually aggressive tumor composed of atypical, neoplastic melanocytes. "Only the module turquoise had a significant enrichment (p = 0.009) of genes whose homologs displayed prognostic value in melanoma, such as Oca2, Samhd1, Nlrc5, Irf1, Ifitm3, Sp100, Dram1, Rtn1, Tcaf2, Parp10, and Grin3a." (PMID 32831131, 2020).
pancreatic cancer (2 papers, 2023 to 2025). "For example, PARP10 and PARP14 are highly upregulated by the type I interferon, IFN-β, in pancreatic cancers." (PMID 40000907, 2025).
cervical cancer (1 paper, 2026). A primary or metastatic malignant neoplasm involving the cervix. "PARP10 promotes cell proliferation and tumorigenesis in cervical cancer cells by alleviating replication stress." (PMID 41326692, 2026).
COVID-19 (1 paper, 2022). A disease caused by infection with severe acute respiratory syndrome coronavirus 2. "Our transcriptomics and qPCR results indicated that a set of PARP family members, including Parp9, Parp10, Parp12, and Parp14, were significantly induced by SARS-CoV-2 infection in mice, similar to those in COVID-19 patients." (PMID 35487885, 2022).
exocrine pancreas cancer (1 paper, 2018). "The depletion of PARP10 by specific shRNAs increased mitochondrial oxidative capacity in cellular models of breast, cervical, colorectal and exocrine pancreas cancer." (PMID 29293500, 2018).
head and neck squamous cell carcinoma (1 paper, 2022). A squamous cell carcinoma that arises from any of the following anatomic sites: lip and oral cavity, nasal cavity, paranasal sinuses, pharynx, larynx, and salivary glands. "Similarly, higher expression of PARP10 was found in head and neck squamous cell carcinoma (HNSCC) (p < 0.001)." (PMID 36313419, 2022).